CXCL12 (C-X-C motif chemokine ligand 12)
Diseases named in the same sentence as CXCL12 in open-access papers (continued):
Sharing a sentence is not in itself a finding about the gene and the disease.
osteosarcoma (continued). "Dysregulation of Wnt/β-catenin expression is responsible for the invasion and metastasis of osteosarcoma, indicating a possible correlation between the CXCR4/CXCL12 axis and Wnt/β-catenin expression in the invasion and metastasis of osteosarcoma." (PMID 26622806, 2015). "CXCR4, the receptor of the chemokine CXCL12, has been reported to promote tumor progression and metastasis in osteosarcoma." (PMID 24040160, 2013). "Inhibition of the CXCR4/CXCL12 pathway by a peptide CXCR4 antagonist reduced the development of osteosarcoma murine lung metastases." (PMID 22518090, 2012). "Similarly, high CXCL12 immunohistochemical expression resulted in a better OS outcome and prognosis in osteosarcoma." (PMID 34834449, 2021). "In osteosarcomas, CXCL12 plays an important role in the homing of cytotoxic T-cells." (PMID 33096815, 2020). "Interestingly, another study showed that DNMT1 inhibitor treatment induced expression of CXCL12 in osteosarcoma tumors." (PMID 30873179, 2019). "In addition, we have previously shown Pim inhibition or silencing to efficiently reduce invasion of PC-3 cells towards MG-63 osteosarcoma cell conditioned medium, where the major chemoattractant is CXCL12." (PMID 26075720, 2015). "In conclusion, expression of the CXCL12 scavenging receptor CXCR7 in the CXCR4-expressing human 143B osteosarcoma cell line enhances its metastatic activity in intratibial primary tumors in SCID mice that predominantly metastasize to the lung and thereby closely mimic the human disease." (PMID 24040160, 2013). "Osteosarcoma cells expressing CXCR4 migrate towards a CXCL12 gradient." (PMID 21234386, 2011). "Human osteosarcoma cell lines also have been found to express high levels of CXCL12." (PMID 21234386, 2011). "Osteosarcoma preferentially metastasizes to lung and bone, tissues with high levels of CXCL12." (PMID 21234386, 2011). "Adhesion of osteosarcoma to endothelial and bone marrow stromal cells is also promoted by CXCL12." (PMID 21234386, 2011). "In TME, many chemokines, such as CXCL12, and many cell phenotypes, such as Tregs and myeloid-derived suppressor cells (MDSCs), may regulate the migration of T cells and contribute to the progression of osteosarcoma." (PMID 39582869, 2024). "We found that, in contrast to our parallel analyses of osteosarcomas, the mechanism of macrophage-driven immune infiltration in Ewing sarcoma was less dependent on CXCL10/CXCL12 than in osteosarcoma." (PMID 40858520, 2025). "The group with the worst EFS and OS for osteosarcoma and Ewing sarcoma, Group 1, was defined by an increase in CXCL5, CXCL12, and MIF." (PMID 41008853, 2025). "As the main matrix component in the microenvironment of osteosarcoma, CAFs secrete a large amount of soluble factors such as IL-6, TGF-β, and CXCL12 (also known as SDF-1)." (PMID 40959080, 2025). "Here, we analyze osteosarcomas via immunohistochemistry for known markers of CAR cells such as leptin receptor (LEPR), B‐cell factor 3 (EBF3), CXCL12, and platelet‐derived growth factor receptor alpha (PDGFRA)." (PMID 35309866, 2022). "In addition to the mechanism by which the elevated local levels of CXCL12 interfere with the cancer cell migration in response to a chemokine gradient towards the site of metastasis, a CXCL12 effect on T cell immune response has also been advocated in osteosarcoma." (PMID 34834449, 2021). "CXCL12 signals through CXCR4, a seven-transmembrane G protein-coupled receptor that is expressed by normal osteoblasts and by malignant cells in osteosarcoma." (PMID 26622806, 2015). "Perissinotto reported that CXCL12 can markedly upregulate the expression and activity of MMP-9 in osteosarcoma." (PMID 18983683, 2008).
osteosarcoma (continued). "Neither CXCR7 transfection of the osteosarcoma cell lines nor supplementing the growth medium with CXCL12 led to sustained cell invasion in the osteosarcoma cell lines alone." (PMID 39592467, 2024). "This study provides the clinical insight that chemokine signaling pathway genes (CCL21, CCL22, CCL24, CXCL11, CXCL12, CXCL13, GNAI2, and RAC2) in proliferating cells might be the potential biomarkers for treatment of osteosarcoma." (PMID 37537613, 2023). "There was not sufficient tissue quantity to assess CXCL12 expression in three high‐grade and two low‐grade osteosarcoma tumors." (PMID 35309866, 2022). "While the CXCL12/CXCR4 signaling stimulates Akt phosphorylation, the use of the Akt inhibitor AKTi-1/2 decreased CXCL12 and CXCR4 mRNA levels in human 143B and murine MOTO osteosarcoma cell lines." (PMID 34440844, 2021). "Indeed, CXCL12 is expressed at high levels in the lung, and CXCR4 expression was high in osteosarcoma-patient samples." (PMID 34830463, 2021). "The C-X-C motif chemokine 12/C-X-C chemokine receptor type 4 (CXCL12/CXCR4) signaling axis is involved in the development of tumors and the metastatic spread of various cancer types, including osteosarcoma." (PMID 26622806, 2015). "Although fibroblastic osteosarcoma specimen OS-7 did not exhibit the readily discernable spatial differences in CXCR4, CXCL12, and MIF expression observed in the other specimens, ligand-receptor analysis did indeed provide evidence of regional differences in the CXCR4 signaling axis." (PMID 39896512, 2025).
acute myeloid leukemia (42 papers, 2012 to 2026). Acute myeloid leukemia (AML) is a group of neoplasms arising from precursor cells committed to the myeloid cell-line differentiation. "Targeting DPP4 in acute myeloid leukaemia (AML) cells altered CXCL12 gradients at three spatial scales." (PMID 42032313, 2026). "So far, the only known exceptions are acute myeloid leukemia cells, which show increased apoptosis following treatment with CXCL12." (PMID 36539774, 2022). "Accumulating studies have been made to understand the association between CXC chemokine ligand-12 (CXCL12)/CXC chemokine receptor 4 (CXCR4) and acute myeloid leukemia (AML)." (PMID 34327063, 2021). "Exosomes derived from Acute Myeloid Leukemia (AML) caused downregulation of the expression of stromal cell factor (SCF) and CXCL12 in stromal cells, both important for normal hematopoiesis which leads hematopoietic stem/progenitor cells (HSPCs) to leave the bone marrow." (PMID 37181754, 2023). "The CXCL12/CXCR4 produced by Prx1+ mesenchymal cells can be a target to eradicate parenchymal leukemia stem cells (LSCs) in acute myeloid leukemia (AML)." (PMID 38841622, 2024). "In 2021, a phase III clinical trial on acute myeloid leukemia (AML) patients showed promising responses when the CXCL12 chemokines were inhibited by DSTAT (dociparstat sodium) in combination with chemotherapy." (PMID 37111629, 2023). "We found that CXCR4hi neutrophils demonstrate a shift towards glycolytic metabolism, and consistent with this a prior report has demonstrated that CXCL12 may play a role in this shift and promote glycolytic reprogramming, as shown in acute myeloid leukemia cells." (PMID 37736772, 2023). "It is well known that CXCR4/CXCL12 interaction leads to acute myeloid leukemia (AML) after chemotherapy and hence the strategy of conjugating the CXCR4 antagonist on the Fe3O4@Pt composite nanozyme’s surface interferes with this axis." (PMID 35711631, 2022). "In hematologic cancers like acute myeloid leukemia (AML), the IGKV1-5/IGKJ3*01 rearrangement in myeloblasts upregulates fLMP and CXCL12, chemotactic factors that drive AML cell migration and dissemination." (PMID 40806736, 2025). "CXCL12/CXCR4 signaling has also been shown to increase autophagic activity and decrease cytarabine-induced apoptosis in acute myeloid leukemia cells." (PMID 37760498, 2023). "For example, elevated levels of SDF-1/CXCL12 and CXCR4 bearing TEVs were found to be present in the peripheral blood and bone marrow plasma samples of patients with acute myelogenous leukemia (AML)." (PMID 33540535, 2021). "CCR5/CCL3 and CXCR4/CXCL12 interactions facilitate the retention of acute myeloid leukemia cells in the skin, and CXCR7/CXCL12 interactions subsequently prolong their survival." (PMID 24591756, 2014). "While we have previously dissected CXCL12 signaling in colon, breast, and pancreas solid tumors, the pharmacologic properties of monomeric and dimeric ligands in hematological malignancies, such as acute myeloid leukemia (AML), remains unknown." (PMID 39253415, 2025). "Thus, at least three adhesion mechanisms, CXCR4/SDF1 (CXCL12), VLA-4/VCAM-1 or fibronectin, and CD44/ligand, function in acute myeloid leukemia migration, retention, and survival." (PMID 22346731, 2012).
Obesity (41 papers, 2013 to 2025). Accumulation of substantial excess body fat. "By contrast, human studies reported decreased CXCL12 mRNA levels with obesity that reverse after bariatric surgery-induced weight loss." (PMID 39848402, 2025). "CXCL12 also contributes to disease progression, including mediation of obesity-associated inflammation and insulin resistance in white adipose tissue." (PMID 39848402, 2025). "In obesity, adipocytes produced several chemokines (Cxcl2, Cxcl12, Ccl2, etc.)recruiting macrophage and neutrophils, causing systemic inflammation, insulin resistance, and the dysfunction of local endothelial cells." (PMID 34722509, 2021). "Furthermore, CXCL12 modulates AT immune cells, promoting AT inflammation and subsequent obesity-associated insulin resistance." (PMID 35406450, 2022). "PPARG, ADAMTS5, TIMP4, ANXA1, AGTR1, and CXCL12 genes are evidently associated with obesity, suggesting that the influence of these genes on obesity may be similar to the influence of fat accumulation in hMSCs." (PMID 34899844, 2021). "Therefore, our results suggest that this polymorphism could increase the proinflammatory action of CXCL12 in subjects with obesity, increasing the risk of T2D, but molecular mechanisms need to be evaluated to confirm this suggestion." (PMID 30764545, 2019). "CXCL12 has been reported as an adipokine that recruits macrophages to AT and induces obesity-related inflammation and systematic insulin resistance." (PMID 35894174, 2022). "In obesity, levels of serum CXCL12 are elevated, and the CXCL12-CXCR4 pathway activates thermogenesis in brown adipose tissue; however, the increased effects of this pathway on white adipose tissue are greater, eventually resulting in insulin resistance." (PMID 34360840, 2021). "A previous study suggests that CXCL12 is normally produced from various neurons and cells, but in obesity, CXCL12 is highly produced from white adipocytes and induces macrophage infiltration in white adipose tissue." (PMID 34360840, 2021). "FA treatment decreased mRNA of ApoD, SEMA3C, CXCL12, and sFRP2, which are closely related to adipocyte differentiation and obesity." (PMID 33915783, 2021). "The CXCL12 rs501120 C, FTO rs9939609 A, and LEP rs7799039 A alleles were significantly associated with T2D in the obesity group under a recessive inheritance model." (PMID 30764545, 2019). "The CXCL12 gene is involved in macrophage recruitment, and it is a factor required for obesity-induced adipose tissue inflammation and systemic insulin resistance." (PMID 30764545, 2019). "In recent years, chemokines such as SDF-1/CXCL12 and fractalkine/CX3CL1 have been shown to be associated with obesity-induced hypothalamic inflammation." (PMID 30618568, 2018). "In contrast, obesity induced with a high-fat diet for 20 weeks in rats resulted in a robust increase in CXCL12 expression in WAT." (PMID 29141038, 2017). "Serum levels of numerous obesity-linked chemokines promoting adipocyte proliferation (TIMP-1) and adipose macrophage infiltration (CXCL1, CXCL2, CXCL12, CCL3, and CCL5) were found to be significant predictors of in vivo hippocampal TSPO signals." (PMID 27578213, 2016). "This is consistent with our analyses of GAL in the PVN, a neuropeptide that is positively related to a HFD and increased in a state of dietary obesity and, while unaffected by CXCL12 as shown here, is stimulated by another chemokine, CCL2." (PMID 27047354, 2016). "Additionally, CXCR7 is expressed in adipose tissue, and its ligands CXCL11 and CXCL12 mediate macrophage chemotaxis and phagocytosis and contribute to inflammation during obesity." (PMID 39582861, 2024). "In murine models of obesity, both the expression and secretion of CXCL12 are elevated." (PMID 39334887, 2024).
Obesity (continued). "In humans, cytokine profiles in the blood can be reversed after bariatric surgery—elevated CCL14, soluble vascular endothelial growth factor receptor 2 (VEGFR2), and platelet-derived growth factor BB in obesity are reduced, and lower CXCL12, CCL11, and CCL27 in obesity are increased." (PMID 38037591, 2023). "Importantly, CXCL12 expression in PPAT stroma increases in cases of obesity and correlates with a decreased survival of patients with PCa." (PMID 35406450, 2022). "This study identifies CXCL12 signaling to be rate-limiting for cancer progression in obesity." (PMID 33753872, 2021). "We found that the CXCL12 rs501120 C allele was a risk factor for T2D in Mexican subjects with obesity and without CD." (PMID 30764545, 2019). "The CXCL12 rs501120 C allele and the FTO rs9939609 A allele were risk factors (rs501120: OR = 1.96, p = 0.02; rs9939609: OR = 2.2, p = 0.04), while LEP rs7799039 was a protective factor (rs7799039: OR = 0.6, p = 0.03) in the obesity group." (PMID 30764545, 2019). "Obesity induces systemic elevation in CXCL12 concentration in the serum." (PMID 30992469, 2019). "Furthermore, this is the first report that highlights an association between polymorphisms in CXCL12 rs501120 and LEP rs7799039 with T2D in Mexican Mestizo adults with obesity." (PMID 30764545, 2019). "Furthermore, we must point at the fact that this is the first report where polymorphisms CXCL12 rs501120 and LEP rs7799039 are associated with T2D in subjects with obesity." (PMID 30764545, 2019). "Further investigation by single cell RNAseq identified four functional molecular endotypes including obesity specific subsets defined by an inflammatory endotype related to immune cell regulation, fibroblast activation and inflammatory signaling, with up‐regulated CXCL12, CFD and CHI3L1 expression." (PMID 37006170, 2023). "In obesity, the expression of CXCR7, CXCL11 and CXCL12 is increased, and CXCR7 neutralizing therapy with an anti-CXCR7 antibody can not only reduce macrophage infiltration and inflammation in obesity but also improve insulin resistance." (PMID 39582861, 2024). "These behaviors suggest that CXCL12 mimics the increase in anxiety induced by prenatal HFD exposure, an effect correlated with maternal obesity and HFD exposure and possibly attributed to the increase in ENK levels in the PVN." (PMID 28567007, 2017). "Secretion of CXCL12 was also detected at low levels in the SVF, with a slight enhancement in obesity." (PMID 26756352, 2016). "Additionally, known as stromal-cell derived factor 1 (SDF-1), CXCL12 is another chemokine that is expressed by PPAT stroma and becomes increased in obesity, positively correlating with a decreased survival in patients with PCa." (PMID 35406450, 2022). "Indeed, obesity-induced EMT in prostate tumors of HiMyc mice was suppressed following the pharmacological depletion of adipose stromal cells, the key source of CXCL12." (PMID 35406450, 2022). "Our results showed that CXCL12 rs501120, LEP rs7799039, and FTO rs9939609 polymorphisms were associated with T2D in subjects with obesity, but not in subjects without obesity." (PMID 30764545, 2019). "HCD-depletion of the Common Lymphoid Progenitor (CLP) and B cell-differentiation-promoting CXCL12 abundant reticular (CAR) cells in the BM additionally reinforces the myeloid/lymphoid bias as does the HCD enhancement of Nestin+ MSCs, which drive the adipocyte bias of the BM niche in obesity." (PMID 36105811, 2022). "The proliferation of macrophages leads to macrophage accumulation in the course of obesity development and is followed by greater migration and aggravated accumulation of macrophages in adipose tissue (mediated by the CCL2/IL-1β/C-X-C motif chemokine ligand 12 (CXCL12) signalling pathway)." (PMID 35328822, 2022).
Obesity (continued). "Additionally, mice lacking CXCR2 show resistance to the onset of obesity-induced disorders of glucose metabolism, and a recent study found that SDF-1/CXCL12, which is secreted from hypertrophic adipocytes, recruits macrophages via CXCR4, which is the receptor of SDF-1/CXCL12, during obesity." (PMID 26197341, 2015). "Interestingly, the expressions of CXCL-12 and Angiopoietin-1 were not reduced by the onset of obesity." (PMID 24595332, 2014).